CRH (corticotropin releasing hormone)
Diseases named in the same sentence as CRH in open-access papers (continued):
Sharing a sentence is not in itself a finding about the gene and the disease.
Sepsis (11 papers, 2011 to 2024). Sepsis is defined as life-threatening organ dysfunction caused by a dysregulated host response to infection. "Moreover, our previous studies established the role of CRH in regulating experimental pneumonia and sepsis caused by S. pneumoniae, implicating it in mediation of host cellular immune and inflammatory responses." (PMID 25904910, 2015). "In acute sepsis-induced critically ill mice (1-day sepsis group), paraventricular mRNA expression of both CRH and AVP was increased as compared with healthy controls (p = 0.04 and p = 0.03, respectively)." (PMID 33593393, 2021). "In the mice, sepsis was found to acutely, though transiently, increase hypothalamic expression of CRH and AVP, followed by an upregulation of both CRH and AVP receptor expression at the pituitary level." (PMID 33593393, 2021). "In prolonged septic mice (7-day sepsis group), mRNA expression of CRH and AVP was comparable to those of healthy control mice (both p > 0.05)." (PMID 33593393, 2021). "In mice, sepsis acutely increased hypothalamic mRNA of CRH (p = 0.04) and AVP (p = 0.03) which subsequently normalized." (PMID 33593393, 2021). "The current study investigated the role of Corticotropin-releasing hormone (CRH) in mediating key markers of pneumococcal virulence as important phenotypic determinants of sepsis and septic shock risks." (PMID 28690980, 2017). "Notably, our studies demonstrated that inhibiting CRH from binding its target receptor CRHR1 caused increased pneumonia and sepsis." (PMID 25904910, 2015). "The findings of these studies are compatible with glucocorticoid-receptor-ligand-binding-induced inhibition of pituitary processing of POMC into ACTH and with preserved CRH/AVP-driven expression of POMC, resulting in elevated circulating POMC levels in sepsis." (PMID 33593393, 2021). "However, they rarely assessed concomitantly the expression of AVP and CRH and their respective receptors as well as relationships between HPA activation and the severity of sepsis." (PMID 22073145, 2011). "This study aimed at investigating the synthesis of corticotropin-releasing hormone (CRH) and vasopressin (AVP) by parvocellular neurons and the antehypophyseal expression of ACTH in human septic shock and in an experimental model of sepsis." (PMID 22073145, 2011). "The finding that CRH expression did not vary among patients according to the duration of septic shock (data not shown) supports that sepsis intensity was a determinant factor." (PMID 22073145, 2011). "It has been shown that LPS down-regulates the mRNA coding for AVP and CRH antehypophyseal receptors; however,the effect of prolonged experimental sepsis on these receptors has not been assessed yet." (PMID 22073145, 2011). "Although direct stimulatory effects of angiotensin 2, CRH, and ACTH on adrenal hormone production are well described, the degree to which each of these peptides contributes to hormone production during sepsis conditions has not been fully elucidated yet." (PMID 28018291, 2016).
Insulin resistance (10 papers, 2014 to 2025). Increased resistance towards insulin, that is, diminished effectiveness of insulin in reducing blood glucose levels. "Insulin resistance occurs during pregnancy due to secretion of hormones by the placenta, including growth hormone, corticotropin-releasing hormone, placental lactogen and progesterone." (PMID 29114267, 2017). "IL-6 also provokes insulin resistance and hyperglycemia by increasing CRH and ACTH release." (PMID 39682557, 2024). "Similarly, IL-6 stimulates the occurrence of insulin resistance and high blood sugar levels by triggering the release of CRH and ACTH." (PMID 39682557, 2024). "GDM is generally a state of both enhanced beta-cell function and marked insulin resistance mediated primarily by placental secretion of diabetogenic hormones, including human placental lactogen, growth hormone, prolactin, corticotropin-releasing hormone (CRH), and progesterone." (PMID 39429984, 2024). "In normal pregnancy, circulating levels of placental hormones, including human placental growth hormone (HPGH), corticotropin-releasing hormone (CRH), human placental lactogen (HPL), prolactin, estrogen, and progesterone, increase and induce insulin resistance." (PMID 40666490, 2025).
neuroendocrine tumors (10 papers, 2013 to 2025). "Approximately 10–20% of CS cases are due to ectopic ACTH syndrome (EAS), which originates from an ACTH-producing or corticotropin-releasing hormone (CRH)-producing neuroendocrine tumor outside of the pituitary." (PMID 35265125, 2022). "Here, we investigated TNFα, CNTF, EGF, dermorphin, dynorphin 17, substance P, somatostatin, corticotropin-releasing hormone, and the native botulinum receptor-binding domain for their ability to direct the botulinum protease into a variety of neuroendocrine tumor cells." (PMID 23638840, 2013). "In fact, it is well known that some neuroendocrine tumors and bronchial carcinoids (despite excessively high ACTH levels) still respond to a CRH stimulus, and this was also true for 8 (31%) of our ECS patients." (PMID 36277711, 2022).
Alzheimer disease (9 papers, 2008 to 2024). A progressive, neurodegenerative disease characterized by loss of function and death of nerve cells in several areas of the brain leading to loss of cognitive function such as memory and language. "An increase of CRH expression is associated with several neurological disorders, such as Alzheimer’s disease (AD), major depression and anxiety disorders." (PMID 31213976, 2019). "In Alzheimer’s disease, a greater cognitive impairment has been found to be associated with lower CSF concentrations of corticotropin-releasing hormone." (PMID 23885764, 2013). "We also set out to investigate and compare CRH levels in other diseases such as Alzheimer’s disease, frontotemporal dementia, vascular dementia and atypical PS." (PMID 39605973, 2024). "We found that CRH was downregulated in SAA+ Lewy body disease compared with SAA− Alzheimer’s disease/frontotemporal dementia/vascular dementia (P = 2.0e−03, AUC = 0.69)." (PMID 39605973, 2024). "Downregulation of CRH expression has also been observed in some neurodegenerative diseases such as Alzheimer disease and Huntington disease." (PMID 18682807, 2008). "Additionally, CRH was decreased in SAA+ Lewy body disease compared with SAA− Alzheimer’s disease/frontotemporal dementia/vascular dementia (with an overlap between groups)." (PMID 39605973, 2024). "The degranulation of mast cells induced by CRH under stress conditions leads to disruption of the blood–brain barrier, which plays an important role in neurological diseases, such as Parkinson’s disease and Alzheimer’s disease." (PMID 35955675, 2022). "Our findings suggest that CRH is downregulated in SAA+ Lewy body disease and atypical PS individuals, compared with SAA− CUI and SAA− Alzheimer’s disease/frontotemporal dementia/vascular dementia." (PMID 39605973, 2024). "The concentrations of corticotropin-releasing hormone (CRH) and corticotropin in cerebrospinal fluid are reduced in patients with Alzheimer’s disease." (PMID 32549368, 2020). "CRH was also assessed in non-Lewy body disease, including Alzheimer’s disease/frontotemporal dementia/vascular dementia and atypical PS." (PMID 39605973, 2024).
anemia (9 papers, 2014 to 2025). A reduction in the number of red blood cells, the amount of hemoglobin, and/or the volume of packed red blood cells. "Apart from oxidative damage, another known biological mechanism indicates that anemia and iron deficiency stimulate the synthesis of corticotropin-releasing hormone (CRH), leading to stress responses in both the mother and the fetus." (PMID 39959784, 2025). "Another possible mechanism for iron deficiency anemia is that iron deficiency stimulates the production of norepinephrine, which then stimulates the production of corticotropin-releasing hormone, potentially limiting fetal growth." (PMID 37546140, 2023). "It is known that anemia and iron deficiency can induce maternal and fetal stress which stimulates the synthesis of corticotropin – releasing hormone (CRH)." (PMID 26613953, 2015). "Anemia may induce maternal and fetal stress and increase the risk of maternal infection stimulating the production of corticotropin-releasing hormone (CRH)." (PMID 36076160, 2022). "Interestingly, iron deficiency and anaemia can also elevate the release of maternal cortisol and placental CRH to cause an increase of cortisol level in the foetus through increasing norepinephrine concentrations." (PMID 24401012, 2014). "Results showed that this FES model induced anemia, increased CRH and ACTH activity in the serum after the FES." (PMID 33542312, 2021). "Ramirez reported that the treatment of anemia in dialysis patients with recombinant human erythropoietin hormone could affect the pituitary-hypothalamic-adrenal axis and increase responses of adrenocorticotropin hormone to corticotropin-releasing hormone." (PMID 30719249, 2018). "In this study, our results confirmed that FES can affect the levels of CRH, ACTH, anemia and GI mucosal injury and bleeding in the FES group." (PMID 33542312, 2021).
Bladder Cancer (9 papers, 2015 to 2026). "Based on these findings, CRH, ANXA10, and IGF2 were considered bladder carcinoma markers, and were therefore detected in urine samples." (PMID 37569864, 2023). "The XPERT© Bladder Cancer Monitor is a test for detecting the five mRNA sequences (ABL1, CRH, IGF2, UPK1B, ANXA10) in urine." (PMID 35804953, 2022). "Based on the detection of five mRNA targets in urine (CRH, IGF2, UPK1B, ANXA10, and ABL1), Xpert Bladder Cancer (Xpert BC) is a recently developed detector for the detection of bladder cancer, which is non-invasive and highly economical." (PMID 33563292, 2021).
endometriosis (9 papers, 2013 to 2022). The growth of functional endometrial tissue in anatomic sites outside the uterine body. "Inflammatory factors, such as IL-1β and corticotropin releasing hormone, play a role in pain associated with deep infiltrating endometriosis, a disorder that is physiologically and histologically similar to adenomyosis." (PMID 35773139, 2022). "Since endometriosis is a stress condition, it would be anticipated that reproductive CRH may play a key-role in pathophysiology of endometriosis, especially when pelvic pain or infertility are associated with the disease." (PMID 23638035, 2013). "Preclinical studies have reported that peripheral CRH is implicated in the pathophysiology of abdominal and pelvic diseases such as IBD, IBS, endometriosis, and bladder disorders." (PMID 35275963, 2022). "Our data provides the first in-vivo demonstration for use of CRHR1 antagonist for the treatment of endometriosis opening the possibility for further exploring CRH signaling as a treatment target for this debilitating disease." (PMID 30427841, 2018). "The similarities between the environmental manipulation and the current pharmacological manipulation, point towards a common mechanism of CRH signaling involvement in endometriosis vesicle development." (PMID 30427841, 2018). "Supporting this assumption, a blunted early morning cortisol response to CRH test was associated with greater menstrual and non-menstrual pain in endometriosis." (PMID 34405378, 2022). "In the same study, we also showed that CRH R1 and CRHR2 are significantly more expressed by the eutopic endometrium of women with endometriosis compared to the corresponding eutopic endometrium of healthy women, implying an increased CRH effect on the eutopic endometrium of women with endometriosis." (PMID 25473847, 2014). "Additionally, the expression of CRH in endometriosis has been correlated with proinflammatory responses influencing thus innate and acquired immune responses." (PMID 23638035, 2013). "Concerning the CRH-related inflammatory profile of endometriosis, progestins could inhibit the CRH-induced inflammation of peritoneal cells in vitro." (PMID 23638035, 2013). "Unidentified endometrial defects in endometriosis could also affect the expression of CRH and UCN resulting in increased expression of CRHR1 and CRHR2 acting as a regulatory mechanism to compensate for the reduced efficiency of proper endometrial function of endometriotic women." (PMID 23638035, 2013). "We also demonstrated that antalarmin prevented the increase in CRH and CRHR1 mRNA within endometriosis vesicles as compared to vehicle treated rats, and this reduction was long lasting (almost 2 months after treatment stopped)." (PMID 30427841, 2018). "We quantified the mRNA for urocortin and CRH, which are the main agonists of the CRHR1 receptor, within developed endometriosis vesicles in rats from both treatment groups using qRT-PCR." (PMID 30427841, 2018). "The expression and function of CRH and UCN have also been found to be impaired in eutopic endometrium of women with endometriosis." (PMID 23638035, 2013). "We further compared the expression of CRH, UCN, CRHR1 and CRHR2 in ectopic endometrium to that in eutopic endometrium of women with endometriosis." (PMID 23638035, 2013). "Immunohistochemistry and western blot analysis were performed in order to identify galectin-1 expression in ectopic and eutopic endometrium of women with and without endometriosis and the regulatory effect of CRH and UCN on galectin-1 expression." (PMID 25473847, 2014). "Despite the fact that CRH/UCN have been implicated in endometriosis – a fact also verified by our results, no data has been reported so far concerning the expression of CRHR1 and CRHR2, the CRH and UCN receptors." (PMID 23638035, 2013).
endometriosis (continued). "This is the first time a study shows that CRHR1 and CRHR2 and specifically the CRHR1β and CRHR2α receptor subtypes are expressed at mRNA and protein level, not only in the endometrium but also at endometriotic sites indicating a potential crucial role of CRH and UCN in endometriosis." (PMID 23638035, 2013). "Interestingly, we found that the expression of CRH, UCN and their receptor subtypes, CRHR1 and CRHR2 is stronger in ectopic endometrium compared to that in eutopic endometrium of women with endometriosis." (PMID 23638035, 2013). "Besides, in endometriosis uterus itself has an altered endometrial receptivity mainly due to local growth factors changes (integrin, LIF, activin, CRH), to hormonal aberrations (ER and PR) and to dysperistalsis of myometrium, due to the association to adenomyosis." (PMID 34405378, 2022). "We then examined how CRH and UCN regulate galectin-1 expression in an endometrial adenocarcinoma cell line, used as a eutopic epithelial endometrium model, aiming to further elucidate the role of these molecules in eutopic endometrium and infertility problems of women with endometriosis." (PMID 25473847, 2014). "This study shows for the first time that CRH and UCN receptor subtypes CRHR1β and CRHR2α are expressed in endometriotic sites and that they are more strongly expressed (p<0.01) in eutopic endometrium of women with endometriosis compared to healthy women endometrium at the mRNA and protein level." (PMID 23638035, 2013). "Moreover, we have recently shown that CRH and UCN receptor subtypes CRHR1b and CRHR2a are expressed in endometriotic sites and that they are more strongly expressed in eutopic endometrium of women with endometriosis compared to healthy women endometrium at mRNA and protein level." (PMID 25473847, 2014). "This can be a possible explanation for why CRH antagonism, but not its agonism has been shown to contribute to pain reduction via epithelial CRHR activation in visceral hypersensitivity, endometriosis, and cystitis, etc.." (PMID 33348790, 2020). "Finally, based on these results, showing that the CRH upregulative effect on galectin-1 is mediated by CRHR1, the potential use of Antalarmin could be reinforced in accessing the immune disequilibrium noticed in eutopic and ectopic endometrium of women with endometriosis." (PMID 25473847, 2014). "CRH, UCN, CRHR1 and CRHR2 mRNA were also more highly expressed in ectopic rather than eutopic endometrium in women with endometriosis." (PMID 25473847, 2014). "CRH, UCN, CRHR1 and CRHR2 mRNA were also more highly expressed in ectopic rather than eutopic endometrium (CRH, UCN, CRHR2α: p<0.01, CRHR1β: p<0.05) and protein (CRH and UCN: p<0.05, CRHR1 and CRHR2: p<0.01) in women with endometriosis." (PMID 23638035, 2013). "However, the relative expression of CRH, UCN and their receptors in eutopic and ectopic endometrium of endometriotic women and in eutopic endometrium of healthy women and women with endometriosis has never been investigated." (PMID 23638035, 2013).
Infertility (9 papers, 2011 to 2025). "Factors that influence the incidence of infertility in adenomyosis are the increase of interleukin (IL-1β) and CRH expression." (PMID 36268444, 2022). "Subsequent studies demonstrated that this may occur via a local corticotropin-releasing hormone (CRH) system, all components of which were then identified in the testes of infertile men." (PMID 36364847, 2022). "CRH and UCN can upregulate the expression of galectin-1 in macrophages, which is involved in the pathology of EMS and infertility." (PMID 41301454, 2025). "Eutopic endometrium highly express CRH, CRHR type 1 and 2, as well as urocortin mRNA and protein, thus suggesting that a deranged CRH and Ucn mRNA expression associated with an impaired CRH-R1 activity may affect the process of decidualization and contribute to infertility in these patients." (PMID 34405378, 2022). "The high expression of CRH in the endometrium of patients with EMS may disrupt the decidualization process, contributing to infertility, while sustained activation of mast cells promotes inflammation and fibrosis." (PMID 41301454, 2025). "Our findings point to a new inflammatory modulator pathway in which CRH, UCN, CRHR1 and CRHR2 are involved acting by an autocrine/paracrine pathway in eutopic and ectopic endometrium potentially affecting the pathogenesis of this benign disease and infertility profile of endometriotic women." (PMID 23638035, 2013).
Melancholic depression (9 papers, 2009 to 2025). "In melancholia, there is an activation of the CRH system including the hypothalamic-pituitary-adrenal (HPA) axis with increased cortisol secretion, the locus coeruleus, and the sympathetic nervous system." (PMID 28931368, 2017). "CRH is known to impair sleep and enhance vigilance, thereby suggesting a causal relationship between shallow sleep and the hyperactivity of the HPA system in melancholic depression." (PMID 19177162, 2009). "Melancholic depression is a chronic stress state that activates cortisol, corticotropin-releasing norepinephrine (NE), and hormone (CRH) pathways without inhibitory feedback mechanisms." (PMID 39200564, 2024). "For instance, HPA axis overdrive, related to an enhanced secretion of CRH and an impaired negative feedback via GC receptors, is most consistently observed in patients with melancholic depression." (PMID 19177162, 2009).